ROS1 (ROS proto-oncogene 1, receptor tyrosine kinase)
Diseases named in the same sentence as ROS1 in open-access papers (continued):
Sharing a sentence is not in itself a finding about the gene and the disease.
lung cancer (continued). "The Archer® FusionPlex®ALK, RET, ROS1 v2 allowed the expected detection of the fusion breakpoints present in the samples: EML4-ALK (E6:A20) and CCDC6-RET (C1:R12) for the commercialized sample, and EML4-ALK (E6:A20) for the human lung cancer cell line H2228." (PMID 28970558, 2017). "Furthermore, crizotinib is a kinase inhibitor for multiple lung cancer oncogene including ALK, c-Met, and ROS1, especially for ROS1-rearranged NSCLC." (PMID 28615068, 2017). "The HCC78 lung cancer cell line is the prototype of “ROS1-addicted” cells, displaying the SLC34A2-ROS1 gene rearrangement that leads to constitutive ROS1 kinase activation and dependence on ROS1 for growth." (PMID 25691052, 2015). "In the current study, we have explored the mutational spectrum of 26 well-established cancer-related genes and ALK, RET, and ROS1 gene fusions by massive parallel sequencing in a large panel of thoroughly histopathologically classified primary LC and LCNEC lung cancers." (PMID 26124082, 2015). "The requirement for co-development and co-approval of CDx in order to get TKIs approved against these RTK (ROS1, RET, NTRK1, AXL, PDGFR-α) rearrangement lung cancer represents the daunting challenge to successfully translate decades of basic science research into benefit of cancer patients." (PMID 24744988, 2014). "From a pathophysiological standpoint, a potential role of ROS1 in HPV‐dependent carcinogenesis may be postulated, supported by experimental evidence demonstrating the regulation of ROS1 expression by HPV oncoproteins E6 and E7, observed in a variety of tumor entities including lung cancer." (PMID 40847660, 2025). "There were no identified cases of ALK or ROS1 translocation amongst lung cancer cases." (PMID 41294703, 2025). "Variant-specific PCR was performed for 744 tumors with a normal 5′/3′-end expression ratio: there were no rearrangements in 172 EGFR/ALK/ROS1/RET/MET-negative lung cancers and 125 pediatric tumors, while NTRK3 fusions were detected in 2/447 (0.5%) non-lung adult malignancies." (PMID 37762506, 2023). "Several oncogenic fusions protein families exist, with ROS proto-oncogene 1 (ROS1), anaplastic lymphoma kinase (ALK), neurotrophic tyrosine receptor kinase (NTRK), and neuregulin 1 (NRG1) being some of the most common partners that are primarily detected in lung cancers." (PMID 37958963, 2023). "RET fusion may be responsible for the pathogenesis in patients with lung cancer without mutations in EGFR, ALK, or ROS1, which may be related to the RET-induced promotion of apoptosis resistance." (PMID 35211155, 2022). "However, at mRNA level, for lung cancer related factor ROS1, CUMS alone did not induce any significant change in ROS1." (PMID 36417428, 2022). "“Non-KRAS oncogene-driven lung cancer subtypes (e.g., ROS1, MET, BRAF, HER2, RET) is less well-studied, however, most of these other non-KRAS molecular subtypes (possibly apart from BRAF V600 mutation and MET gene alteration) are associated with a light-to-never smoking history." (PMID 34575691, 2021). "ROS1-rearranged lung cancers benefit from first-line crizotinib therapy; however, clinical and molecular factors that could affect crizotinib efficacy in ROS1-rearranged lung cancers are not yet well-elucidated." (PMID 34511132, 2021). "Moreover, there is a relatively high percentage of AYAs with lung cancer who never smoked and have driver mutations, such as EGFR, ALK, KRAS, and ROS1." (PMID 33218178, 2020). "Meanwhile, 6 cases of putative lung cancers were examined, but no ROS1 rearrangement was detected." (PMID 30443294, 2018). "The Ion AmpliSeq RNA Lung Cancer Research Fusion Panel is based on an amplicon target enrichment approach that allows amplification and detection of 70 known fusion transcripts for the ALK, RET, ROS1, and NTRK1 genes using a couple of primers specific of each fusion." (PMID 28970558, 2017).
lung cancer (continued). "However, due to the low incidence of ROS1 rearrangement in lung cancer, no study has comprehensively compared these three methods for ROS1-fusion detection." (PMID 25742289, 2015). "The authors also reported on 6 NRAS mutant lung carcinoma cell lines and their sensitivity to the MEK inhibitors selumetinib and trametinib and their resistance to erlotinib (EGFR-TK inhibitor), crizotinib (ALK/MET/RON/ROS1 inhibitor) and linsitinib (IGF-1R inhibitor)." (PMID 25277205, 2014). "Similarly, lung cancers frequently overexpress ALK and ROS1, which may be inhibited by GTx-186 or crizotinib." (PMID 24386191, 2013). "In addition to traditional surgical treatment and chemotherapy, targeted therapies represented by EGFR inhibitors, ALK inhibitors, ROS1 inhibitors and immunotherapies represented by PD‐1/PD‐L1 inhibitors and CTLA‐4 inhibitors are playing an increasingly critical role in the treatment of lung cancer." (PMID 40845073, 2025). "However, as the human ROS1 gene promoter lacks κB elements and not all human lung cancer cell lines express ROS1 protein, including A549 and H1299 which are fusion-negative cell lines, we further investigated the role of CD82 in epithelial lung cancer cell growth." (PMID 34503110, 2021). "The case with ROS1 fusion did not receive a matched therapy because the NGS result came out too late and the patient died of lung cancer." (PMID 38399524, 2024). "Of these fusions, 16 (including ALK, ARAF, BRAF, FGFR1, FGFR3, RET, and ROS1) and 21 (including ABL1, GNAS, JAK2, and NRG1) were classified as either related to lung cancer, or as oncogenes that have not been reported in lung cancer, respectively." (PMID 36153311, 2022). "Top-down approaches are exemplified by the discovery of NRF2 activations, which were detected in all lung cancer tissues regardless of the status of other biomarkers, such as EGFR, ALK, ROS-1 and other genetic alterations." (PMID 35806042, 2022). "The findings of an electronic search for publications using RET-FISH in lung cancer were compared with the results obtained at the Grenoble University Hospital where 784 EGFR-, KRAS-, ALK-, and ROS1-negative NSCLCs were tested by RET break-apart FISH and confirmed by RNA-sequencing (RNA-seq)." (PMID 39507413, 2024).
non-small cell lung carcinoma (264 papers, 2013 to 2026). A group of at least three distinct histological types of lung cancer, including non-small cell squamous cell carcinoma, adenocarcinoma, and large cell carcinoma. "ROS1, one of fifty-eight receptor tyrosine kinases, has been implicated in various cancer subtypes, including glioblastoma, non-small-cell lung cancer, and cholangiocarcinoma." (PMID 41754770, 2026). "ROS proto-oncogene 1 (ROS1) fusion is a rare but important driver mutation in non-small cell lung cancer, which usually shows significant sensitivity to small molecule tyrosine kinase inhibitors." (PMID 39854762, 2025). "Our results revealed unique mutation rates in the EGFR, KRAS, and ROS1 genes among non-small cell lung cancer patients." (PMID 38828424, 2024). "ROS1 as a driver mutation is observed in approximately 1%–2% of all non-small cell lung cancer (NSCLC)." (PMID 38425761, 2024). "According to several studies, ROS1 rearrangement is associated with thrombotic risk in non-small cell lung cancer (NSCLC)." (PMID 36167545, 2022). "Agents targeting proteins encoded by mutated EGFR, ALK, and ROS1 genes significantly improve the prognosis of advanced oncogene-driven non-small cell lung cancer (NSCLC)." (PMID 34067376, 2021). "We also assayed for ALK and ROS1 mutations in 211 patients with non-small cell lung cancer through ARMS-PCR." (PMID 32429938, 2020). "Evaluation of key driver mutations, such as those found in the genes encoding EGFR, anaplastic lymphoma kinase (ALK), and ROS proto-oncogene 1 (ROS1), has now become routine practice in the diagnostic pipeline of individuals with advanced non-small cell lung cancer (NSCLC)." (PMID 38144524, 2023). "ROS proto-oncogene 1, receptor tyrosine kinase (ROS1), encodes an orphan receptor tyrosine kinase and is vulnerable to intrachromosomal or interchromosomal rearrangements in several tumor types including non-small-cell-lung cancer." (PMID 31565069, 2019). "ROS-1 positive non-small cell lung cancer (NSCLC) constitutes a lesser-known yet targetable subcategory of lung malignancies, contributing 1-2% of cases." (PMID 41798534, 2026). "Its primary application in clinical settings is for the treatment of advanced non-small-cell lung cancer characterized by anaplastic lymphoma kinase-positive and/or ROS1 fusion gene-positive status." (PMID 41578599, 2026). "SMARCA4-deficient non-small cell lung cancer (SMARCA4-dNSCLC) is an aggressive malignancy with poor prognosis, rarely harboring EGFR, ALK, or ROS1 alterations." (PMID 41684594, 2026). "Multiple ROS1 fusion proteins have been discovered to play an important role in a variety of human cancers including glioblastoma, non-small-cell lung cancer, and breast cancer." (PMID 39827240, 2025). "ROS1 rearrangement are well-established oncogenic drivers in non-small cell lung cancer (NSCLC), where they confer sensitivity to tyrosine kinase inhibitors (TKIs) such as crizotinib." (PMID 41179684, 2025). "Regarding non-small-cell lung cancer (NSCLC), multiple studies have shown that patients with rearrangements in the anaplastic lymphoma kinase (ALK) and c-ros oncogene 1 (ROS1) genes are at an increased risk of VTE events." (PMID 40004816, 2025). "Mutations in EGFR, KRAS, and BRAF are common in non-small cell lung cancer (NSCLC), while ALK, ROS1, and RET rearrangements define distinct molecular subtypes." (PMID 41012430, 2025). "Entrectinib, a recently approved multikinase inhibitor indicated for advanced ROS1-positive non-small cell lung cancer (NSCLC), has demonstrated significant survival benefits in metastatic disease." (PMID 40822018, 2025). "Beyond EGFR mutations, clinically relevant genetic alterations in non-small cell lung cancer (NSCLC) include fusions involving ALK, ROS1, RET, and NTRK1/2/3." (PMID 41301039, 2025).
non-small cell lung carcinoma (continued). "In 2019, entrectinib (Rozlytrek) joined the list of tumor-agnostic therapies approved for NTRK fusion-positive tumors and ROS1-positive non-small cell lung cancer (NSCLC), including those with central nervous system metastases." (PMID 40075649, 2025). "First-line therapy referenced by NSCL-30 NCCN Clinical Practice Guidelines in Oncology (NCCN Guidelines) for Non-Small Cell Lung Cancer, Version 6.2024 for treating ROS1 rearrangement is included for comparison." (PMID 40271313, 2025). "ROS1 rearrangement a distinct molecular subtype of non-small cell lung cancer that is amenable to targeted therapeutic interventions." (PMID 40826797, 2025). "Ponatinib, bosutinib, and repotrectinib are FDA-approved for the treatment of acute lymphoblastic leukemia, childhood chronic myeloid leukemia, and ROS1-positive non-small cell lung cancer, respectively." (PMID 41198656, 2025). "Repotrectinib is a novel-generation multitargeted tyrosine kinase inhibitor (TKI), with data available for ROS1-positive Non-Small Cell Lung Cancer (NSCLC) through the ongoing TRIDENT-1 trial." (PMID 40243903, 2025). "ROS1 tyrosine kinase inhibitors (TKIs) have shown significant efficacy in advanced ROS1-rearranged non-small cell lung cancer (NSCLC)." (PMID 40949148, 2025). "•Herein, we present a female patient with advanced non-small cell lung cancer harboring the MPRIP-ROS1 fusion gene, an extremely rare ROS1 rearrangement." (PMID 40678598, 2025). "Entrectinib is an oral TKI targeting NTRK, ROS1, and ALK fusions, approved by the FDA and EMA for ROS1-positive non-small cell lung cancer and NTRK fusion-positive solid tumors, including TC, in patients ≥ 12 years." (PMID 40507281, 2025). "Targeted molecular treatments for advanced non-small cell lung cancer (NSCLC) have been revolutionized by the identification of oncogenic activation in specific tyrosine kinases, such as EGFR, ALK, and ROS1, using driver mutations as biomarkers." (PMID 39851952, 2025). "Lastly Crizotinib, targeting ALK and ROS1 in non-small cell lung cancer, frequently leads to visual disturbances." (PMID 41568391, 2025). "ROS1 fusions are relatively rare drivers in non-small cell lung cancer (NSCLC), occurring in 1-2% of cases." (PMID 40371229, 2025). "Background and Objectives: ROS1 rearrangement is a rare but targetable alteration in non-small-cell lung cancer (NSCLC), occurring in 1–2% of cases." (PMID 40142301, 2025). "Recently, an incidence of VTE greater than 30% has been described in patients with pancreatic cancer and in specific molecular subtypes of non-small cell lung cancer with ROS-1 and ALK rearrangement." (PMID 40359988, 2025). "ROS1 and RET fusions are targetable mutations that occur in a subset of patients with non-small cell lung cancer (NSCLC)." (PMID 39907599, 2025). "In the treatment of non-small-cell lung cancer, inhibitors targeting the ROS1 fusion gene have become a major focus of research." (PMID 40584293, 2025). "Other important driver mutations such as anaplastic lymphoma kinase (ALK) rearrangement has a reported prevalence of 2- 7 % and rearrangements of the ROS1 gene occurring in 1–2 % of non-small cell lung cancers (NSCLCs)." (PMID 40112503, 2025). "Mutations in SMARCA4 have been shown to co-exist with KRAS mutations but are mutually exclusive from common targetable non-small cell lung carcinoma (NSCLC) oncogenes, including EGFR, ALK, MET, ROS-1, and RET." (PMID 40406754, 2025). "Repotrectinib, crizotinib, and entrectinib are tyrosine kinase inhibitors approved for ROS1-positive advanced non-small-cell lung cancer." (PMID 40075596, 2025). "In non-small cell lung cancer (NSCLC), molecular testing for EGFR mutations, ALK or ROS1 rearrangements, BRAF V600E mutations, and KRAS G12C mutations is now standard practice." (PMID 41010962, 2025).
non-small cell lung carcinoma (continued). "A study of repotrectinib versus crizotinib with locally advanced or metastatic TKI-naïve ROS1-positive non-small cell lung cancer, TRIDENT-3 [NCT06140836], is a phase three trial which started in December of 2023." (PMID 39195309, 2024). "ROS1 rearrangements are observed in approximately 1.5% of non-small cell lung cancers, and even for this well-known indication only a few available ROS1 inhibitors have been subjected to a proper registration procedure." (PMID 38612902, 2024). "This drug demonstrates efficacy in treating ALK-positive and ROS1-positive non-small cell lung cancer (NSCLC)." (PMID 39001541, 2024). "EGFR mutations, ALK translocations, ROS1 aberrations and BRAF mutations are now routinely evaluated in advanced non-small cell lung cancer (NSCLC), especially in adenocarcinoma." (PMID 38200537, 2024). "SAF-189s is a potent ALK/ROS1 inhibitor that is currently in clinical development for treating advanced ALK+/ROS1+ non-small cell lung cancer (NSCLC)." (PMID 39081957, 2024). "Entrectinib serves as an oral inhibitor targeting the tyrosine kinases TRKA/B/C, ROS1, and ALK, and is utilized in the treatment of solid tumors that harbor NTRK gene fusions as well as non-small cell lung cancer featuring ROS1 mutations." (PMID 39629004, 2024). "Given the favorable clinical activity of crizotinib, ROS1 TKI therapy has become the first-line treatment for advanced non-small cell lung cancer (NSCLC) patients initially testing positive for ROS1 fusion." (PMID 38273343, 2024). "Entrectinib is an inhibitor of NTRK, ALK, and ROS1 that is currently approved in patients with ROS1-positive non-small cell lung cancer and patients with solid tumors and NTRK gene fusions." (PMID 38438731, 2024). "ROS1 rearrangement has been found not only in the epithelial tumors, such as non-small cell lung cancer (NSCLC), ovarian cancer, gastric adenocarcinoma, and colorectal cancer, but also in some mesenchymal tumors, such as IMT, angiosarcoma, and leiomyosarcoma." (PMID 37735390, 2023). "It was approved by the FDA in 2019 for adult patients with ROS1-positive metastatic non-small cell lung cancer." (PMID 37240178, 2023). "Some of these fusions or mutations showed, to some degree, clinical significance, for instance, like ALK positive non-small cell lung cancer (NSCLC), ROS1 positive NSCLC has more high risk of central nervous system metastasis." (PMID 36998041, 2023). "ROS1 fusion is an infrequent, but attractive target for therapy in patients with metastatic non- small-cell lung cancer." (PMID 37237384, 2023). "Entrectinib is a kinase inhibitor approved for ROS1-positive metastatic non-small cell lung cancer (NSCLC) and neurotrophic receptor tyrosine kinase gene fusion positive solid tumors." (PMID 38202651, 2023). "ROS1 is among the molecular biomarkers which should be analyzed at diagnosis in non-small cell lung cancer (NSCLC)." (PMID 38134118, 2023). "In turn, ALK and ROS1 rearrangements are detected in approximately 4.5% and 1% of non-small cell lung cancer patients, respectively." (PMID 37298856, 2023). "Crizotonib is a small molecule tyrosine kinase inhibitor targeting ALK and is currently approved for adult patients with ALK- or ROS1-positive, metastatic non-small cell lung cancer (NSCLC)." (PMID 36980578, 2023). "Two ROS1 tyrosine kinase inhibitors have been approved for ROS1 fusion positive (ROS1+) non-small cell lung cancer (NSCLC) tumors." (PMID 37853341, 2023). "Entrectinib have been approved by FDA in 2019 and by Europe in 2020 clinically for the chemotherapy of solid tumors with positive NTRK fusions and non-small cell lung cancers with positive fusions of ROS1." (PMID 36699581, 2022). "Detection of the ROS1 rearrangement is mandatory in patients with advanced or metastatic non-small cell lung cancer (NSCLC) to allow targeted therapy with specific inhibitors." (PMID 35303812, 2022).